HSPA1L (heat shock protein family A (Hsp70) member 1 like)
Description:
Molecular chaperone implicated in a wide variety of cellular processes, including protection of the proteome from stress, folding and transport of newly synthesized polypeptides, activation of proteolysis of misfolded proteins and the formation and dissociation of protein complexes. Plays a pivotal role in the protein quality control system, ensuring the correct folding of proteins, the re-folding of misfolded proteins and controlling the targeting of proteins for subsequent degradation. This is achieved through cycles of ATP binding, ATP hydrolysis and ADP release, mediated by co-chaperones. The affinity for polypeptides is regulated by its nucleotide bound state. In the ATP-bound form, it has a low affinity for substrate proteins. However, upon hydrolysis of the ATP to ADP, it undergoes a conformational change that increases its affinity for substrate proteins. It goes through repeated cycles of ATP hydrolysis and nucleotide exchange, which permits cycles of substrate binding and release. Positive regulator of PRKN translocation to damaged mitochondria.
Synonyms: HSP70-Hom; hum70t; HSP70-1L; HSP70T
Tractability: Small molecule: a structure with a bound ligand is known. Antibody: its Gene Ontology location is reachable by antibodies, with medium confidence. PROTAC: ubiquitination databases record sites on it; its protein half-life has been measured.
Safety:
Unwanted effects reported when the protein is acted on. In parentheses: how it was acted on, where the effect was seen, and who reports it.
chance of severe hypersensitivity (source: ClinPGx)
chance of severe hypersensitivity to carbamazepine treatment (source: ClinPGx)
Gene: Protein-coding gene on chromosome 6 (31,809,619 to 31,815,788, reverse strand). Ensembl gene ENSG00000204390.
Subcellular location (Human Protein Atlas): Annulus; Flagellar centriole; Vesicles; Calyx; Perinuclear theca
Pathways (Reactome):
Cellular responses to stimuli: Attenuation phase; HSF1-dependent transactivation; HSP90 chaperone cycle for steroid hormone receptors (SHR) in the presence of ligand; Regulation of HSF1-mediated heat shock response
Immune System: PKR-mediated signaling
Gene Ontology:
Molecular function: heat shock protein binding; protein binding; ubiquitin protein ligase binding; ATP hydrolysis activity; protein folding chaperone; ATP binding
Biological process: positive regulation of establishment of protein localization to mitochondrion; protein refolding; response to unfolded protein; response to stress
Cellular component: blood microparticle; COP9 signalosome; cytosol; nucleoplasm; nucleus; plasma membrane; cell body; zona pellucida receptor complex
Genetic constraint (gnomAD): Loss-of-function variants: 25 observed, 32.6 expected, observed/expected ratio (o/e) 0.77, 90% interval 0.56 to 1.07. The upper end of that interval is the gene's LOEUF score, 1.07, which puts it in group 4 of 6, group 1 being the genes least tolerant of losing a copy. Missense variants: 709 observed, 831.16 expected, observed/expected ratio (o/e) 0.85, 90% interval 0.8 to 0.91. Synonymous variants: 293 observed, 330.22 expected, observed/expected ratio (o/e) 0.89, 90% interval 0.81 to 0.98.
Homologues: Orthologues: macaque HSPA1L (99% identical), chimpanzee HSPA1L (98% identical), dog HSPA1L (96% identical), guinea pig HSPA1L (95% identical), mouse Hspa1l (95% identical), rat Hspa1l (95% identical), pig HSPA1L (87% identical), Caenorhabditis elegans F44E5.4 (67% identical), Caenorhabditis elegans F44E5.5 (67% identical), Caenorhabditis elegans hsp-70 (66% identical), rabbit HSPA1L (54% identical), Drosophila melanogaster Hsp110 (30% identical), and 1 more. Paralogues in human: HSPA1A (89% identical), HSPA1B (89% identical), HSPA8 (83% identical), HSPA2 (82% identical), HSPA6 (79% identical), HSPA5 (63% identical), HSPA9 (50% identical), HSPA4 (35% identical), HSPA4L (33% identical), HSPH1 (33% identical), HYOU1 (30% identical), HSPA14 (28% identical), and 1 more.